RNU6-1076P (RNA, U6 small nuclear 1076, pseudogene)
Gene: Small nuclear RNA gene on chromosome 19 (223,158 to 223,261, reverse strand). Ensembl gene ENSG00000222329.
Homologues: Orthologues: chimpanzee U6 (100% identical), macaque U6 (91% identical), pig U6 (84% identical), pig U6 (78% identical), dog U6 (77% identical). Paralogues in human: RNU6-1100P (100% identical), RNU6-1118P (100% identical), RNU6-1217P (100% identical), RNU6-355P (100% identical), RNU6-447P (100% identical), RNU6-785P (100% identical), RNU6-791P (100% identical), RNU6-860P (100% identical), U6 (100% identical), RNU6-1054P (99% identical), RNU6-1199P (99% identical), RNU6-1319P (99% identical), and 1289 more.